CRP (C-reactive protein)
Diseases named in the same sentence as CRP in open-access papers (continued):
Sharing a sentence is not in itself a finding about the gene and the disease.
viral infections (continued). "Of 18 children with an infection of undetermined etiology, 10 (55.6%) had a diagnosis of tonsillitis negative for group A Streptococcus, and 7 (39%) tested positive for a respiratory virus but could not be categorized as viral infection only, most often due to an unusually high CRP level." (PMID 35080443, 2022). "Laboratory findings indicated that C-reactive protein ≥ 100.0 mg/L [81/184 (44.0%) vs. 93/151 (60.9%), P = 0.002] and procalcitonin (≥ 0.5 ng/mL) [79/162 (48.8%) vs. 83/136 (61.0%), P = 0.036] were more frequent in patients with nonviral coinfections than in patients with only viral infections." (PMID 35685411, 2022). "Therefore, it is suggested that NP may be increased independent of IL-6 and CRP elevation in cases of viral infection." (PMID 35529699, 2022). "Thus, the relative lack of CRP response seen in viral infections and Type I IFN-driven autoimmune diseases can be attributed to an IFN-α-dependent downregulation of CRP transcription, as well as CRP gene polymorphisms, which are over-represented among patients with SLE." (PMID 34945133, 2021). "Finally, CRP is a nonspecific marker of inflammation and might be influenced by several conditions, such as bacterial or viral infection, chronic autoimmune disease, severe stress, and surgical treatments." (PMID 34070592, 2021). "This reassurance led a wide range of our respondents to trust that a low CRP level indicated good health (in simple terms, a low CRP level indicates the absence of a bacterial infection, even if a viral infection is present; and the level might also be depressed by prior antibiotic use)." (PMID 29499522, 2018). "Moreover, an old study demonstrated that there CRP concentrations could reach 225 mg/L in acute tularemia, but there were also low CRP values); therefore, the CRP’s behavior in tularemia resembled tuberculosis, and it did not always aid in the differentiation of tularemia from viral diseases." (PMID 37873776, 2023). "In contrast to conventional inflammatory markers like CRP, serum PCT has higher sensitivity and specificity in bacterial infections and does not increase in patients with sterile inflammation or viral infection." (PMID 37964301, 2023). "Importantly, the high serum levels of CRP, which are normally lacking in viral infections, but observed in the severe cases since the beginning of COVID-19 pandemic, may be explained by the high production of IL-6 accompanying the Macrophage Activation Syndrome." (PMID 37388734, 2023). "Four days before Day78 when CRP was 8 mg/L, he started to have a fever and was diagnosed with a common cold at clinic; however, because the neutrophil count and CL-O2−· was low, his data may indicate that he had a more virulent virus infection rather than a common cold." (PMID 34267248, 2021). "It was found that CRP and PCT are elevated in patients with HFRS and CCHF, but these biomarkers are not specific and not sufficient to predict virus infection severity." (PMID 27348219, 2016). "Unlike other inflammatory markers (e.g., CRP), PCT level does not respond to viral infection or sterile inflammation." (PMID 25145785, 2014). "Because fever, rash, neutropenia and slightly elevated levels of CRP (4-5-fold), ESR, and liver enzymes are common features of viral infections, viral serology was initially searched and found negative." (PMID 25574175, 2014). "A host-protein score (BV score) for differentiating bacterial from viral infection that combines the expression levels of TNF-related apoptosis-induced ligand, interferon gamma-induced protein-10, and C-reactive protein exhibited a negative predictive value (NPV) of 98% in prior studies." (PMID 36389361, 2022). "Additionally, CRP expression was induced in bacterial infections, whereas TRAIL and IP-10 expression were induced during viral infections (as compared to non-infectious controls)." (PMID 27486746, 2016).
viral infections (continued). "Numerous studies have confirmed its superiority over C-reactive protein (CRP) and other markers, citing its rapid increase following a bacterial stimulus and its relative specificity, as its levels are not significantly elevated in most viral infections or non-infectious inflammatory states." (PMID 41557164, 2026). "Despite the fact that the CRP has a predictive value for CVD in patients with rectal cancer, it is a nonspecific marker of inflammation and may be impacted by other conditions, such as bacterial or viral infections, that have not been analyzed in our cohort." (PMID 38074681, 2023). "As a result, there were few patients with confirmed bacterial and viral infections and the majority of patients were classified as probable bacterial or viral RTI on the basis of proxy radiographic and biochemical tests (chest radiography and CRP), rather than microbiologic tests." (PMID 29252995, 2017). "Furthermore, the established biochemical markers of infections, including C-reactive protein (CRP) and procalcitonin (PCT), may also be elevated during non-bacterial infectious toxicities such as drug reactions, inflammatory toxicities, viral infections, and tumor lysis." (PMID 37919603, 2024).
chronic kidney disease (499 papers, 2008 to 2026). Impairment of the renal function secondary to chronic kidney damage persisting for three or more months. "Since PTX3 is more sensitive than hs-CRP in distinguishing stages of DN, it holds promise as a more reliable biomarker for assessing kidney function and predicting the risk of chronic kidney disease (CKD) in diabetic patients." (PMID 40299501, 2025). "In recent studies, it has been seen that CRP has been associated with poorer outcomes in several diseases like hypertensive kidney and cardiovascular complications, acute and chronic kidney diseases, and diabetic neuropathy." (PMID 40362763, 2025). "Inflammatory mucosa was associated with high CRP levels, use of PPIs, coexisting chronic renal failure, use of antitumor drugs and small bowel wall thickening (> 4.15 mm) shown on CT." (PMID 40230560, 2025). "Other important predictors of all-cause mortality were older age, the presence of chronic kidney disease, currently active malignancy, and atrial fibrillation, lower percentage of lymphocytes, and higher C-reactive protein levels." (PMID 37755581, 2024). "EPCs were also associated with older age, some comorbid conditions (chronic kidney disease, chronic lung disease, and immunocompromise), worse pulmonary ordinal scale at baseline, and increasing levels of CRP and IL-6." (PMID 39271151, 2024). "Another study showed that markers of inflammation (including high-sensitivity C-reactive protein, tumor necrosis factor- α receptor 2, white blood cell count, and interleukin-6) predict the long-term risk of developing chronic kidney disease." (PMID 39677959, 2024). "According to our final model, the independent predictors of all-cause mortality were older age, the presence of chronic kidney disease, currently active malignancy, and atrial fibrillation, lower percentage of lymphocytes, and higher C-reactive protein levels." (PMID 37755581, 2024). "A previous study on 41 patients with chronic kidney disease found that patients with higher levels of CRP, ferritin, and D-dimer were at higher risk of developing AKI than patients with lower levels of these biomarkers." (PMID 38378528, 2024). "This is consistent with a previous finding that extracellular free thiols were positively associated with eGFR, and inversely associated with BMI and CRP levels in chronic kidney disease (CKD) patients." (PMID 39702549, 2024). "There is evidence indicating that high-sensitivity CRP is associated with higher suPAR levels in chronic kidney disease, where high-sensitivity CRP reflects low-grade, chronic inflammation, while normal CRP typically signals more acute inflammatory responses." (PMID 39540961, 2024). "For example, it has been shown in patients with chronic kidney disease that an increased MUFA/SFA ratio in blood lipids is associated with elevated circulating levels of CRP, suggesting the potential for exacerbation of inflammation." (PMID 38053162, 2023). "The current regression model analysis revealed that the suPAR level significantly improved discrimination power to identify the risk of chronic kidney disease, being more significant than that with well-established biomarkers, such as C-reactive protein (CRP)." (PMID 37108340, 2023). "Elevated CRP has been demonstrated in patients with chronic kidney disease, and it has also been implicated in kidney ischemia/reperfusion injury." (PMID 35355862, 2022). "The antibody, ziltivekimab, has so far been effective at reducing CRP levels in patients with chronic kidney disease, who are at increased risk of developing CVD and are contraindicated for alternative therapies such as colchicine." (PMID 36339576, 2022). "Two variables were independently associated to death at 21 days: CRP at admission (OR = 1.013, P = 0.004) and chronic kidney disease (OR = 4.631, P = 0.025)." (PMID 33838684, 2021).
chronic kidney disease (continued). "Hospital mortality was independently associated with increasing age, male sex, history of chronic kidney disease, increasing baseline C-reactive protein level, and dyspnoea at presentation." (PMID 33564474, 2021). "The risk of death was also associated with age, C-reactive protein concentration, cancer and chronic kidney disease." (PMID 34015025, 2021). "Introduction and Aims: Elevated plasma levels of C-reactive protein (CRP) are closely associated with progressive renal injury in patients with chronic kidney disease (CKD)." (PMID 34671208, 2021). "Independent associates of AKI were chronic kidney disease, C-reactive protein (CRP) and ventilation support." (PMID 33025516, 2021). "History of chronic kidney disease and high CRP at admission were independently associated with death." (PMID 33838684, 2021). "In end-stage renal disease there is a strong association between inflammation marker C-reactive protein (CRP) and risk of death and cardiovascular events." (PMID 33326471, 2020). "Recently, it has been associated with all-cause of mortality in geriatric patients diagnosed with chronic kidney disease, associated with higher C-reactive protein in patients with end-stage renal disease, and erythropoietin resistance." (PMID 31207869, 2019). "C-reactive protein (CRP) has been shown to be associated with arterial stiffness in an apparently healthy cohort and in subjects with end stage renal disease (ESRD)." (PMID 28759613, 2017). "In conclusion, better VO2max was associated with lower frequency of elevated CRP levels in subjects with chronic kidney disease." (PMID 22566996, 2012). "Pruritus associated with chronic kidney disease has been shown to be associated with elevated levels of C-reactive protein and other inflammatory cytokines." (PMID 23006933, 2012). "Furthermore, allopurinol treatment in patients with chronic kidney disease can not only reduce CRP levels but also lower cardiovascular risk and delay the progression of kidney disease." (PMID 39371339, 2024). "In addition, risk of poor in-hospital survival was significantly associated with chronic kidney disease (HR = 6.36, 95% CI 1.87–21.67, P = 0.0031) and CRP > 20 mg/L (HR = 5.02, 95% CI 1.72–14.66, P = 0.0032)." (PMID 35287602, 2022). "Interestingly enough, significant associations between patients with chronic kidney disease and CRP and WBC values were only observed prior to explantation." (PMID 36139954, 2022). "In the univariate binary logistic regression, the PaO2/FiO2 ratio, underlying chronic liver disease, underlying chronic kidney disease, initial hemoglobin, C-reactive protein (CRP), lactate, total bilirubin, first day peak airway pressure and dynamic driving pressure were significant factors." (PMID 33922592, 2021). "Results of the Chronic Renal Insufficiency Cohort (CRIC) showed that higher FGF23 levels are associated with higher levels of the inflammatory markers CRP, IL6, TNFα, and fibrinogen and with a higher odds ratio for severe inflammation independent of mineral metabolism and renal function." (PMID 34208131, 2021). "In our study, logistic regression analysis indicated that chronic kidney disease, C-reactive protein >100 IU/L, and serum albumin <3 gm/dl were independent risk factors associated with mortality in melioidosis patients–(OR = 14.0, OR = 6.964, and OR = 8.0, respectively)." (PMID 34285680, 2021). "In addition, chronic inflammation is associated with coronary artery calcification, which is evidenced by the association between C-reactive protein level and coronary artery calcification in patients with end-stage renal disease (ESRD) on peritoneal dialysis." (PMID 32433039, 2020). "Also, we recently revealed the pathogenic role for CRP in acute and chronic kidney diseases via a NF-κB-dependent mechanism." (PMID 30202420, 2018).
chronic kidney disease (continued). "There were statistically significant differences in age, causes of end-stage renal disease, dialysis vintage, body mass index, total cholesterol, C-reactive protein and KT/V among users of D[Ca] ≥3.0 mEq/L and 2.5 mEq/L, but the standardized difference was less than 10%." (PMID 29968801, 2018). "In addition to CRP, there are also a number of other salivary biomarkers that have been associated with cIMT and also with age, diabetes, and chronic kidney disease (CKD)." (PMID 30647796, 2018). "This study included 264 participants with high CV risk, moderate to severe chronic kidney disease (CKD), and hs-CRP > 2 mg/L." (PMID 37629496, 2023). "In the prospective CARE study, elevated levels of sTNFR2 and CRP were associated with early renal function loss in subjects with chronic kidney disease (CKD)." (PMID 29445381, 2018). "Chronic kidney disease (CKD) is associated with increased procoagulants, including cystatin C, C-reactive protein, interleukin-6, tumor necrosis factor-α soluble receptor 1, intercellular adhesion molecule-1, fibrinogen, and factor VIII." (PMID 30115029, 2018). "Multivariate analysis identified age, chronic kidney disease, low albumin, elevated creatinine, CRP, the MLR, and hospital stay as independent mortality predictors." (PMID 41816734, 2026). "There were also trends toward significance for smoking (OR (95% CI): 4.79 (0.92–24.92), p = 0.062), chronic kidney disease (OR (95% CI): 6.00 (0.85–42.26), p = 0.072) and CRP levels (OR (95% CI): 1.02 (1.00–1.04), p = 0.055) in univariate analysis." (PMID 41375908, 2025). "In the final model, red blood cell count, preoperative CRP, chronic kidney disease, operative time, body mass index, blood transfusion, and estimated blood loss were selected based on bootstrap inclusion frequency." (PMID 40870423, 2025). "Multivariate regression analysis of clinical characteristics indicated that arterial lactate, WBC, lymphocytes, CRP and chronic kidney disease were independent predictors." (PMID 39611805, 2025). "The final model incorporated red blood cell count, preoperative CRP, chronic kidney disease, operative time, body mass index, blood transfusion, and estimated blood loss." (PMID 40870423, 2025). "In orthopedic trauma surgery, incorporating routinely available predictors such as CRP, blood transfusion, and chronic kidney disease ensures both usability and relevance." (PMID 40870423, 2025). "Independent mortality predictors included age, chronic kidney disease, cardiogenic shock, and log‐transformed NT‐proBNP, hs‐troponin I, and CRP." (PMID 41321756, 2025). "HDL-C/CRP has been shown to reflect the severity of chronic kidney disease and to be predictive of its progression." (PMID 38443857, 2024). "The trial, conducted among individuals with chronic kidney disease and elevated CRP, showed dose-dependent reductions in these biomarkers over 24 weeks, with no significant adverse effects observed." (PMID 38256497, 2024). "This large-scale cardiovascular outcome study aims to investigate the impact of ziltivekimab in patients with chronic kidney disease, elevated high-sensitivity CRP, and established cardiovascular disease." (PMID 38256497, 2024). "Factors associated with patient fatality or prolonged hospitalization included older age, cancer, chronic kidney disease, higher Charlson and McCabe indices, elevated C-reactive protein, and low albumin concentrations." (PMID 38792341, 2024). "In the Chronic Renal Insufficiency Cohort (CRIC) study, biomarkers of inflammation (IL-1β, IL-1 receptor antagonists, IL-6, TNF-α, CRP, and fibrinogen) were negatively associated with renal function and positively associated with proteinuria." (PMID 39126619, 2024). "Deceased patients with end-stage renal disease presented higher levels of both cfDNA and inflammatory markers (IL-6 and C-reactive protein), compared with living subjects." (PMID 37685683, 2023).